TMEM168 (transmembrane protein 168)
Description:
Plays a key role in maintaining the cardiac electrical stability by modulating cell surface expression of SCN5A. May play a role in the modulation of anxiety behavior by regulating GABAergic neuronal system in the nucleus accumbens (By similarity).
Synonyms: DKFZp564C012; FLJ13576
Tractability: Antibody: UniProt predicts a signal peptide or a membrane-spanning region. PROTAC: ubiquitination databases record sites on it; its protein half-life has been measured.
Gene: Protein-coding gene on chromosome 7 (112,762,377 to 112,790,715, reverse strand). Ensembl gene ENSG00000146802.
Subcellular location: Nucleus membrane
Subcellular location (Human Protein Atlas): Golgi apparatus; Cytosol
Gene Ontology:
Molecular function: sodium channel regulator activity
Cellular component: nuclear membrane; transport vesicle
Genetic constraint (gnomAD): Loss-of-function variants: 40 observed, 54.64 expected, observed/expected ratio (o/e) 0.73, 90% interval 0.57 to 0.95. The upper end of that interval is the gene's LOEUF score, 0.95, which puts it in group 4 of 6, group 1 being the genes least tolerant of losing a copy. Missense variants: 771 observed, 868.2 expected, observed/expected ratio (o/e) 0.89, 90% interval 0.84 to 0.94. Synonymous variants: 282 observed, 309.56 expected, observed/expected ratio (o/e) 0.91, 90% interval 0.83 to 1.
Gene-disease validity (ClinGen):
ClinGen rates the evidence that TMEM168 causes each of these diseases.
Brugada syndrome (autosomal dominant): Disputed. A genetically heterogeneous condition characterized by complete or incomplete right bundle branch block accompanied by ST elevation in leads V1-V3.
Homologues: Orthologues: chimpanzee TMEM168 (99% identical), macaque TMEM168 (99% identical), pig TMEM168 (98% identical), dog TMEM168 (98% identical), guinea pig TMEM168 (97% identical), rabbit TMEM168 (97% identical), rat Tmem168 (96% identical), mouse Tmem168 (95% identical), tropical clawed frog tmem168 (82% identical), zebrafish tmem168b (63% identical), zebrafish tmem168a (59% identical).
Diseases named in the same sentence as TMEM168 in open-access papers:
TMEM168 is named in the same sentence as 11 diseases in open-access papers, as found by Europe PMC text mining. Sharing a sentence is not in itself a finding about the gene and the disease. The quoted sentences say what the papers report.
Anxiety (2 papers, 2017 to 2023). Intense feelings of nervousness, tension, or panic often arise in response to interpersonal stresses. "In the present study, we found that the increased METH related molecule TMEM168 in the nucleus accumbens, induced anxiety in the elevated plus-maze and light/dark box tasks, and resulted in sensorimotor gating deficit in the auditory PPI task." (PMID 29211814, 2017). "We identified TMEM168 in the NAc as a novel target to induce anxiety and schizophrenia-like symptoms, by inhibiting the GABAergic system in the NAc." (PMID 29211814, 2017). "The NAc-TMEM mice reported no change in the locomotor activity, cognitive ability, social interaction, and depression-like behaviors; however, TMEM168 overexpression enhanced anxiety in the elevated-plus maze and light/dark box test." (PMID 29211814, 2017). "TMEM168 overexpression in the NAc increased anxiety in mice, such as entries (p < 0.05, t = 2.844) and time (p < 0.05, t = 2.2.253) on open arms in the elevated plus-maze) as well as time in the light box in light/dark box tasks (p < 0.05, t = 2.964)." (PMID 29211814, 2017). "In summary, TMEM168 overexpression in the NAc neurons could induce a decrease in the extracellular GABA levels in the NAc, with effects on both anxiety levels and sensorimotor gating ability." (PMID 29211814, 2017). "Furthermore, the pharmacological action of anxiety reducing drug, diazepam, which is known to facilitate GABAergic transmission by binding GABAA receptors, reversed the TMEM168 overexpression-induced anxiety as measured in both the elevated plus-maze and light/dark box tasks." (PMID 29211814, 2017).
glioblastoma (2 papers, 2022 to 2023). The most malignant astrocytic tumor (WHO grade IV). "A growing number of studies revealed that TMEMs were differentially expressed among human cancers, including TMEM116 and TMEM229A in lung cancer, TMEM205 in hepatocellular carcinoma, TMEM168 in glioblastoma, and TMEM180 in colorectal cancer." (PMID 36313638, 2022).
methamphetamine dependence (1 paper, 2017). A drug dependence that is a psychological dependency on the regular use of methamphetamine. "Our studies suggest that the TMEM168-regulated osteopontin system is a novel target pathway for the therapy of methamphetamine dependence, via regulating the dopaminergic function in the nucleus accumbens." (PMID 29026117, 2017).
schizophrenia (1 paper, 2017). A major psychotic disorder characterized by abnormalities in the perception or expression of reality. "Although the neurotransmissions in these accumbal relevant regions of the NAc-TMEM mice are needed to be analyzed in the next study, the functional roles of accumbal TMEM168 in the METH-induced schizophrenia-like behaviors were demonstrated firstly in the present experiment." (PMID 29211814, 2017).
tumor (1 paper, 2024). "It has been shown that some TMEM proteins are involved in tumor growth, proliferation, migration, and cell invasion through the Wnt/ b-catenin pathway, such as TMEM48, TMEM45B, and TMEM168, whereas TMEM170B and TMEM98 act as tumor development inhibitors through the same pathway." (PMID 38850316, 2024).
TMEM168 also shares sentences with these, for which no sentence is quoted: lung carcinoma (2 papers); breast carcinoma (1); cancer (1); colorectal cancer (1); depression (1); hepatocellular carcinoma (1).